LINC01440 (long independently transcribed non-coding RNA 1440)
Gene: Long non-coding RNA gene on chromosome 20 (55,302,988 to 55,684,915, forward strand). Ensembl gene ENSG00000235166.
Diseases named in the same sentence as LINC01440 in open-access papers:
LINC01440 is named in the same sentence as 1 disease in open-access papers, as found by Europe PMC text mining. Sharing a sentence is not in itself a finding about the gene and the disease.
LINC01440 shares sentences with these, for which no sentence is quoted: cancer (1 paper).